UIMC1 (ubiquitin interaction motif containing 1)
Description:
Ubiquitin-binding protein. Specifically recognizes and binds 'Lys-63'-linked ubiquitin (PubMed:19328070, Ref.38). Plays a central role in the BRCA1-A complex by specifically binding 'Lys-63'-linked ubiquitinated histones H2A and H2AX at DNA lesions sites, leading to target the BRCA1-BARD1 heterodimer to sites of DNA damage at double-strand breaks (DSBs). The BRCA1-A complex also possesses deubiquitinase activity that specifically removes 'Lys-63'-linked ubiquitin on histones H2A and H2AX. Also weakly binds monoubiquitin but with much less affinity than 'Lys-63'-linked ubiquitin. May interact with monoubiquitinated histones H2A and H2B; the relevance of such results is however unclear in vivo. Does not bind Lys-48'-linked ubiquitin. May indirectly act as a transcriptional repressor by inhibiting the interaction of NR6A1 with the corepressor NCOR1.
Synonyms: RAP80; X2HRIP110
Tractability: PROTAC: UniProt records ubiquitination sites on it; ubiquitination databases record sites on it; its protein half-life has been measured.
Gene: Protein-coding gene on chromosome 5 (176,902,226 to 177,022,636, reverse strand). Ensembl gene ENSG00000087206.
Subcellular location: Nucleus
Subcellular location (Human Protein Atlas): Nuclear bodies; Nucleoplasm
Pathways (Reactome):
DNA Repair: Nonhomologous End-Joining (NHEJ); Processing of DNA double-strand break ends; Recruitment and ATM-mediated phosphorylation of repair and signaling proteins at DNA double strand breaks
Cell Cycle: G2/M DNA damage checkpoint
Metabolism of proteins: Metalloprotease DUBs
Gene Ontology:
Molecular function: histone binding; K63-linked polyubiquitin modification-dependent protein binding; protein binding; ubiquitin-modified histone reader activity; DNA binding
Biological process: DNA repair-dependent chromatin remodeling; double-strand break repair; mitotic G2 DNA damage checkpoint signaling; negative regulation of DNA-templated transcription; positive regulation of DNA repair; response to ionizing radiation; mitotic G2/M transition checkpoint; regulation of DNA repair; DNA repair
Cellular component: BRCA1-A complex; nuclear body; nucleoplasm; nucleus; site of double-strand break
Genetic constraint (gnomAD): Loss-of-function variants: 34 observed, 80 expected, observed/expected ratio (o/e) 0.43, 90% interval 0.32 to 0.57. The upper end of that interval is the gene's LOEUF score, 0.57, which puts it in group 2 of 6, group 1 being the genes least tolerant of losing a copy. Missense variants: 813 observed, 869.72 expected, observed/expected ratio (o/e) 0.93, 90% interval 0.88 to 0.99. Synonymous variants: 279 observed, 301.99 expected, observed/expected ratio (o/e) 0.92, 90% interval 0.84 to 1.02.
Homologues: Orthologues: chimpanzee UIMC1 (97% identical), macaque UIMC1 (95% identical), dog UIMC1 (88% identical), rabbit UIMC1 (87% identical), pig UIMC1 (86% identical), guinea pig UIMC1 (83% identical), mouse Uimc1 (76% identical), rat Uimc1 (72% identical), tropical clawed frog sh2d4b (32% identical).
Diseases named in the same sentence as UIMC1 in open-access papers:
UIMC1 is named in the same sentence as 23 diseases in open-access papers, as found by Europe PMC text mining. Sharing a sentence is not in itself a finding about the gene and the disease. The quoted sentences say what the papers report.
breast carcinoma (10 papers, 2008 to 2021). "Only few studies have addressed the role of UIMC1 or FAM175A mutations in breast cancer susceptibility." (PMID 24025454, 2013).
ovarian carcinoma (6 papers, 2012 to 2025). A malignant neoplasm originating from the surface ovarian epithelium. "We observed that olaparib promotes the expression of SMARCA4, UIMC1, and SLX4 in ovarian cancer cells." (PMID 40240356, 2025). "In conclusion, these findings suggested that USP28/SOX9 positively regulates the expression of DDR genes (SMARCA4, UIMC1, and SLX4) by binding to their promoters in ovarian cancer cells." (PMID 40240356, 2025). "Our further research showed that USP28/SOX9 modulate the HRR activity of ovarian cancer by regulating SMARCA4, UIMC1, and SLX4 expression." (PMID 40240356, 2025). "ChIP-Seq analysis revealed that SOX9 binds to the promoters of key DNA damage repair (DDR) genes (SMARCA4, UIMC1, and SLX4), thereby regulating DDR processes in ovarian cancer." (PMID 40240356, 2025).
glioma (1 paper, 2020). A benign or malignant brain and spinal cord tumor that arises from glial cells (astrocytes, oligodendrocytes, ependymal cells). "Recurrent deletions in previously unknown glioma genes NT5C2, ADGRL2, and UIMC1 were observed whilst SUB1, CES1, and ITGA6 were frequently methylated in human LGGs; frequent CNVs in these genes were also present in human GBMs." (PMID 32727536, 2020).
Premature ovarian insufficiency (1 paper, 2021). Amenorrhea due to loss of ovarian function before the age of 40. "So far, large-scale GWAS have identified several SNPs, such as rs11668344 (BRSK1), rs365132 (UIMC1) and rs16991615 (MCM8), relevant for age at natural menopause or premature ovarian insufficiency (POI) in the general population." (PMID 34572825, 2021).
tumor (12 papers, 2012 to 2025). "The expression of COPB2, DCTN4, RYK, TARS, and UIMC1 indicated association with the change of fraction of immune cells in LSCC patients; two genes, COPB2 and RYK, indicated different expression in various tumor stages of LSCC." (PMID 35715770, 2022).
UIMC1 also shares sentences with these, for which no sentence is quoted: cancer (6 papers); lymphoma (2); bladder cancer (1); breast and ovarian cancer (1); ciliopathies (1); colon cancer (1); colorectal cancer (1); diffuse large B-cell lymphoma (1); esophageal cancer (1); esophageal squamous cell carcinoma (1); familial ovarian cancer (1); Fanconi anemia (1); Hydrocephalus (1); lung adenocarcinoma (1); ovarian tumor (1); pancreatic cancer (1); Sepsis (1); triple-negative breast carcinoma (1).